MIR3197 (microRNA 3197)
Synonyms: hsa-mir-3197
Gene: MicroRNA gene on chromosome 21 (41,167,557 to 41,167,629, forward strand). Ensembl gene ENSG00000263681.
Homologues: Orthologues: chimpanzee MIR3197 (100% identical).